VDAC2P2 (VDAC2 pseudogene 2)
Gene: Processed pseudogene on chromosome 12 (9,036,344 to 9,037,244, forward strand). Ensembl gene ENSG00000255776.
Diseases named in the same sentence as VDAC2P2 in open-access papers:
VDAC2P2 is named in the same sentence as 1 disease in open-access papers, as found by Europe PMC text mining. Sharing a sentence is not in itself a finding about the gene and the disease. The quoted sentences say what the papers report.
atrial fibrillation (1 paper, 2021). A disorder characterized by an electrocardiographic finding of a supraventricular arrhythmia characterized by the replacement of consistent P waves by rapid oscillations or fibrillatory waves that vary in size, shape and timing and are accompanied by an irregular ventricular response. "Another study related to cardiovascular diseases presented VDAC2P2 as a lncRNA potentially involved in atrial fibrillation (AF)." (PMID 33921034, 2021).